ENSG00000212589
Synonyms: LOC124900297
Gene: Small nucleolar RNA gene on chromosome 10 (113,820,459 to 113,820,590, forward strand). Ensembl gene ENSG00000212589.
Gene Ontology:
Biological process: RNA processing
Cellular component: nucleolus
Homologues: Orthologues: rat LOC120102662 (77% identical), rat LOC120099020 (73% identical), rat LOC120100438 (73% identical), rat LOC120101319 (73% identical), rat LOC120100413 (73% identical), rat LOC120094514 (70% identical), rat LOC120103343 (69% identical), rat LOC120101330 (68% identical), rat LOC120103336 (68% identical), mouse Gm26184 (67% identical), rat LOC120096406 (66% identical), rat LOC120095452 (64% identical), and 7 more. Paralogues in human: SNORA17B (58% identical).